S100A9 (S100 calcium binding protein A9)
Diseases named in the same sentence as S100A9 in open-access papers (continued):
Sharing a sentence is not in itself a finding about the gene and the disease.
infection (148 papers, 2005 to 2026). The state of being infected such as from the introduction of a foreign agent such as serum, vaccine, antigenic substance or organism. "Inflammatory macrophages (cluster 3) exhibited a highly interconnected set of unique DEGs encoding for neutrophil granule proteins such as s100a8 and s100a9 that are upregulated in neutrophils in response to infection." (PMID 38149246, 2023). "S100A9 belongs to the family of danger-associated molecular patterns induced upon infection, injury or inflammation to initiate the first rapid inflammatory response 34,36." (PMID 35198063, 2022). "Application of S100A8/A9 immediately after infection and after 11 h led to a complete loss of the differences between S100A9−/− and WT mice in neutrophil recruitment to the intravascular, interstitial and alveolar compartments of the lung." (PMID 36497202, 2022). "Similar findings were observed in Trypanosoma cruzi-infected mice, which displayed an enhanced cardiac expression of S100A8 and S100A9 upon infection in association with an increased presence of MDSC in the heart." (PMID 34065891, 2021). "Correspondingly, transcription of Reg3γ as well as the genes encoding the antimicrobial factors S100a8 and S100a9 was also strongly induced (100-fold) during infection, potentially to promote host defense." (PMID 31848276, 2019). "Calprotectin is a heterodimer composed of S100A8 and S100A9, two members of the large S100 family of calcium-binding proteins implicated in defense against infection." (PMID 24204275, 2013). "Although A. baumannii rarely causes lethal infection in immunocompetent mice, S100A9−/− mice exhibit a significant increase in mortality over a 72-hour time course." (PMID 23236280, 2012). "Presumably associated with PMNs' infiltration, s100a8 and s100a9 expressions in the lung mainly occurred at 3 days post–infection." (PMID 21423669, 2011). "Moreover, enhanced TB resistance of S100A9-KO mice was associated with higher numbers of lung BCFs at the chronic stage of infection." (PMID 36674664, 2023). "Given that S100A9 might play an antibacterial role by chelating the zinc necessary for growth of pathogenic bacteria, METTL9 mediated S100A9 methylation may participate in the innate immune response to infection." (PMID 37671148, 2023). "S100A9 participates in innate immunity and mediates inflammatory response caused by infection." (PMID 35565618, 2022). "We could observe only minor differences in the numbers of mucosal macrophages or neutrophil granulocytes or in mRNA copy numbers of inflammatory markers like S100a9 and Reg3g during the course of infection between control and double deficient mice." (PMID 34497340, 2022). "Therefore, systemic and long-term suppression of S100A8/S100A9 may increase susceptibility to infections." (PMID 41476978, 2025). "S100a9 normally functions in complex with S100a8 in response to infection by inducing pro-inflammatory cytokines, reactive oxygen species, and nitric oxide." (PMID 39510801, 2025). "In SLE patients, the expression of S100A8 and S100A9 on the surface of dendritic cells is notably increased, especially during periods of infection." (PMID 39877611, 2025). "S100A9 is significantly upregulated in infections, metabolic inflammation, immune system dysfunction and degenerative diseases." (PMID 40478888, 2025). "The expression of Mmp8, S100a8 and S100a9 in the mNeu and immNeu of infection groups was predominantly decreased in the blood." (PMID 40874427, 2025). "S100A9 is an acute-phase protein whose plasma levels change in response to inflammation, infection, and tissue injury." (PMID 40568587, 2025). "Nonetheless, the present results underscore the importance of future clinical studies carefully monitoring for signs of infection and evaluating the risk–benefit ratio of S100A8/S100A9 inhibition in patients with GLM." (PMID 41476978, 2025).
infection (continued). "The infection outcome in S100a9−/− mice closely resembled that of WT mice, indicating that C. rodentium is resistant to calprotectin and that S100a9−/− mice do not phenocopy the survival impairment observed in Il22−/− mice." (PMID 38557196, 2024). "S100-A9 is upregulated during infection, inflammation, and disease, and is highly expressed at sites of inflammation and injury." (PMID 39014464, 2024). "Although, we observed an overall decrease in the alveolar macrophage population in the BALF of both WT and S100A8/A9, there was a significant increase in number of infiltrating inflammatory macrophages (F4/80+ CCR2+ cells) in S100a9 KO mice upon infection." (PMID 37624851, 2023). "infection studies using a global S100a9 knockout (deficient of both S100A8 and S100A9 proteins) and wild type (WT) mice." (PMID 37624851, 2023). "Numbers of alveolar macrophages were only transiently reduced in S100A9 KO mice on day 1 post-infection, while reaching normal levels on day 2 post-infection." (PMID 37467233, 2023). "As expected, WT→KO chimeric mice showed significantly increased S100A9 levels in BALF post-infection, while KO→WT chimeras again demonstrated low levels of S100A9 protein in BALF." (PMID 37467233, 2023). "Challenge of WT and S100A9 KO mice with a higher infection dose (107 CFU S. pneumoniae) confirmed the striking susceptibility of S100A9 KO mice to pneumococcal challenge." (PMID 37467233, 2023). "S100A9, belonging to the S100 family, plays an important role in trauma, infection, high temperature, stress and many other inflammatory processes." (PMID 36769382, 2023). "Seven infection/inflammation-related proteins in our assay, S100A9, VIM, LGALS1, APCS, MMP9, LDHA, and CRP, were elevated in TB-PEs and the other-infectious-PEs." (PMID 35197508, 2022). "reuteri+SL1344 group further confirm that the S100A8/S100A9–NF-κB pathway played an important role in infection of mice induced by S. Typhimurium SL1344." (PMID 35658572, 2022). "Expression of S100A8 and S100A9 is massively upregulated during infection and inflammation protecting the body from the spread of pathogens." (PMID 35198063, 2022). "FPS-ZM1 treatment maintained S100A9 levels in the lung on day 4 after infection relative to vehicle-treated mice." (PMID 35076028, 2022). "Intriguingly, although the transcriptional profiles of the caput in sham- and UPEC-infected mice were very similar, upregulation of a few infection-related genes such as S100a8, S100a9, and Slfn4 was indicative for the presence of UPEC in the infected caput." (PMID 36515584, 2022). "S100A9 gene is considered to play crucial functions in participating innate immunity and mediating the inflammatory response during infection-induced host inflammation." (PMID 35401691, 2022). "With the infection of larval E. granulosus, there were higher expression levels of many inflammatory factors in splenic B cells, such as Cxcl5, Il1r1, S100a8, S100a9, and CD14, which form a complex network of immune regulation." (PMID 35548052, 2022). "Upon injury or infection, S100A9 is abundantly released and participates in the recruitment of leukocytes and cytokine secretion, which in turn play critical role in modulating inflammation and tissue injury." (PMID 33549095, 2021). "For this, WT and S100A9-/- mice were IP-infected with C. albicans and fungal dissemination into different organs was determined 24 h post infection." (PMID 33717058, 2021). "The increase in S100A9 and HMGB1 was associated positively with the female sex and negatively with infection status in COPD patients during an exacerbation." (PMID 33567747, 2021). "Calprotectin, also known as S100A8/S100A9 heterocomplex, is a protein involved in the innate immune response to infection." (PMID 34054868, 2021). "Most notably, survivors with mild disease had an ∼30-log2-fold reduction in the expression of S100A8 and S100A9 early after infection, whereas survivors with severe disease exhibited an ∼2-log2-fold reduction." (PMID 34372693, 2021).
infection (continued). "Increased level of S100A9 is related to the infection of multiple pathogens and participates in disease progression by regulating inflammatory immunity." (PMID 34093546, 2021). "We found expression of HLA-DPB1, a MHC class II gene, in CD14+ monocytes was inversely correlated with severity of infection, whereas expression of alarmins (e.g., S100A9) in CD14+ monocytes was positively correlated with severity." (PMID 33765435, 2021). "While IP-infected WT mice again succumbed to infection within 72 h, survival of S100A9-/- mice ranged at approximately 50% at this time point post infection." (PMID 33717058, 2021). "We found an increased total number of cells in the airways, including neutrophils, DCs, and T cells, as well as enhanced expression of Cxcl1, S100a8, and S100a9 after RV‐A1b infection in Mir146a/b−/‐ mice compared to wt mice." (PMID 34185416, 2021). "Nevertheless, similar to Paq treatment, mouse weight continued to decrease during infection in both WT and S100A9-/- mice." (PMID 33717058, 2021). "For this purpose, we IP-infected WT and S100A9-/- mice with C. albicans, collected livers 24 h post infection and prepared H & E stained liver sections." (PMID 33717058, 2021). "S100A9, which is known to be upregulated during infection and inflammation, was also present in the ATG5 interactome." (PMID 33024031, 2020). "The S100A8/S100A9 heterodimer, also known as calprotectin, is abundantly expressed by neutrophils and markedly increased during infection, tissue damage, neutrophil extracellular trap formation (NETosis) and cellular necrosis." (PMID 32107497, 2020). "The elevated level of S100A8/S100A9 amplifies inflammation and enhances the inflammatory response in infection, making it a potential therapeutic target in anti-inflammatory strategies." (PMID 32076015, 2020). "A key way the host restricts the availability of zinc at sites of infection is through the S100A8/S100A9 heterodimer calprotectin, which is produced by a range of host cells but predominantly by neutrophils at infection sites." (PMID 32817386, 2020). "H37Rv infection induced much higher LXA4 (****p < 0.0001) and lower LTB4 production in WT RAW264.7 cells (***p < 0.001) after infection for 12 h than in the S100A9–/– RAW264.7 cells." (PMID 32457723, 2020). "Among these genes, S100A9 participates in innate immunity and mediates the inflammatory response during infection-induced inflammation." (PMID 32547963, 2020). "S100A9 is expressed abundantly in neutrophils and is able to regulate the ability of neutrophils to respond acutely to infection." (PMID 32117815, 2020). "RAW264.7 cells or BMDMs (WT or S100A9–/–) were infected with bacteria [H37Rv, H37RvΔ1768, Ms, Ms (pMV), or Ms (pMV-1768)] for the mixed infection assay." (PMID 32457723, 2020). "Ubiquitination of InlC controls the level of S100A9 and the S100A9-dependent host response to infection." (PMID 31848284, 2019). "A similar trend was observed in HeLa cells transfected with a plasmid expressing HA-tagged S100A9, whose S100A9 levels were higher upon infection with Listeria expressing native InlC than upon infection with Listeria expressing InlC-Kall or InlC-K224." (PMID 31848284, 2019). "During Litomosoides sigmodontis infection, BALB/c mice were found to have an increase in S100a9 transcription in lung tissue within hours after the infection." (PMID 31412915, 2019). "Given that host ubiquitination of InlC contributes to the host response to infection, we next sought to determine if S100A9 was involved in this response." (PMID 31848284, 2019). "After C. difficile colonization and infection, Zn levels were significantly reduced in WT mice compared to that in S100A9−/− mice, confirming a role of CP in limiting Zn availability during CDI." (PMID 31744916, 2019). "Host ubiquitination of InlC stabilizes S100A9, triggers ROS production by neutrophils, and restricts infection." (PMID 31848284, 2019).
infection (continued). "In EBOV-infected NHPs, S100A9 was increased 8.43 fold from pre-infection levels by Day 6 PI, and S100A8 levels increased by 4.95 fold." (PMID 30774579, 2019). "We found that infection with the strain producing InlC-K224, which leads to rapid S100A9 degradation, triggers weaker ROS production by neutrophils than the WT strain." (PMID 31848284, 2019). "There are other types of cells that can release S100A8 and S100A9 upon infection; for example, during hidradenitis suppurativa infection, keratinocytes are one of the most important sources of S100 proteins." (PMID 29942307, 2018). "We then elucidate the role of S100A9 by infection with AdsiS100A9 for silencing its expression in AdHBx-infected HepG2 cells." (PMID 29795379, 2018). "We then investigated the role of S100A9 by infection with recombinant adenoviruses carrying S100A9-siRNA gene (AdsiS100A9) for silencing its expression in AdHBx-infected HepG2 cells." (PMID 29795379, 2018). "S100a8 and S100a9 recruitment results in the elimination of Leishmania and knockout mice experiencing a more severe infection." (PMID 27490109, 2016). "The peak of the S100A9-dependent inflammation was 8–10 days post-infection and this timing coincided with the highest levels of mS100A9 recovered from the BAL fluid (∼1–10 μg)." (PMID 25706559, 2015). "QRT-PCR confirmed significant induction of RegIIIβ, RegIIIγ, Lcn2, Ltf, S100a8, and S100a9 mRNA levels following infection." (PMID 26658437, 2015). "To functionally characterize the role of S100A8/A9, we challenged wildtype (WT) and S100A9-/- mice with S. Typhimurium and determined bacterial loads and inflammation 2- and 5- days post infection." (PMID 25860480, 2015). "Genetic studies showed that the DDX21-TRIF signaling pathway is required for S100A9 gene expression/production during infection." (PMID 24391503, 2014). "During infection, while 10%–25% of S100A9 protein is released, the rest is localized inside the cell." (PMID 24391503, 2014). "In the current study we have demonstrated that extracellular S100A9 protein functions as a host-derived molecular pattern during infection." (PMID 24391503, 2014). "Extracellular S100A9 contributes to production of pro-inflammatory mediators during infection as evident from reduced TNF and IL-6 levels in the lung of S100A9 antibody treated mice." (PMID 24391503, 2014). "Calprotectin consists of the Ca2+-binding proteins S100a8 and S100a9 that are induced in epithelial cells in response to tissue damage and infection." (PMID 23241281, 2012). "The presence of such high levels of S100A8 and S100A9 following infection, and the importance of these proteins for expanding MDSC, suggests one likely mechanism to account for the accumulation of HV-68 induced CD11b + Gr1+ cells in the spleen." (PMID 22507226, 2012). "This study is the first to investigate the expression, localization, and role of S100A9 in a local E. coli-induced infection of the urinary tract system." (PMID 20976233, 2010). "Next, we performed double staining for Ly6G with S100A9 to study colocalization in kidney tissue slides obtained from WT mice, 24 hours after infection." (PMID 20976233, 2010). "We only found significantly reduced KC and MIP-2 levels in bladder homogenates from S100A9 KO mice, respectively 24 hours after infection with 9×108 CFU and 48 hours after infection with 4.5×108 CFU." (PMID 20976233, 2010). "In kidney homogenates, only TNF-α levels were significantly reduced in S100A9 KO mice, 24 hours after infection with 4.5×108 CFU." (PMID 20976233, 2010). "Inflammation and infection models often show increased levels of S100A9." (PMID 39534554, 2024). "With regards to SARS-CoV-2, S100-A9 is increased during infection." (PMID 39014464, 2024).
infection (continued). "The expression levels of Lcn2, which encodes for the antimicrobial protein lipocalin-2, and of S100a8 and S100a9, whose gene products together form the antimicrobial protein calprotectin, were increased during infection but were comparable between WT mice and Il22−/− mice." (PMID 38557196, 2024). "Plasma S100A8 and S100A9 had high specificity and sensitivity in predicting infection." (PMID 39575241, 2024). "infection significantly increased mortality of S100a9 KO mice compared to WT mice." (PMID 37624851, 2023). "Corresponding to the severe histopathology, S100A9 KO mice challenged with a low infection dose of 6 x 106 CFU S. pneumoniae showed a significantly decreased survival of just 10% by day 3 post-infection, compared to 100% survival for S. pneumoniae-challenged WT mice." (PMID 37467233, 2023). "Furthermore, Cxcl3 (FC = 41.4) and the antimicrobial proteins S100a9, S100a8 (FC = 204.3 and 90.7), and Ccl3l1 (FC = 28.5) were strongly upregulated by infection." (PMID 38251349, 2023). "S100A9 secretion is induced during infection, injury and inflammation." (PMID 35198063, 2022). "S100A9 immunostaining also showed widespread neutrophilic infiltration in the lungs, liver, kidneys, and adrenal glands during fatal infection, which was not limited to the clusters of infiltrated immune cells but widespread throughout the functional areas of each organ." (PMID 35437094, 2022). "Finally, we verified that elevated S100A9 following UPEC-infection contributed to maintain the M2 polarization of TMs through the activation of PI3K/Akt pathway." (PMID 34764959, 2021). "S100A9 is up-regulated in various models of inflammation and infection." (PMID 34884728, 2021). "The results corroborated that 24 h post infection liver damage was consistently higher in IP-infected WT mice, even though fungal burden was significantly lower in livers of WT mice than in those of S100A9-/- mice." (PMID 33717058, 2021). "In contrast, 5-LO expression showed no significant changes between H37Rv- and H37RvΔ1768-infection in S100A9–/– RAW264.7 cells (right), suggesting that Rv1768 stimulates macrophage 5-LO expression after infection for 12 h, and that this stimulation depends on S100A9." (PMID 32457723, 2020). "In the present work, we report that InlC is monoubiquitinated on K224 upon infection of cells and provide evidence that ubiquitinated InlC interacts with and stabilizes the alarmin S100A9, which is a critical regulator of the immune response and inflammatory processes." (PMID 31848284, 2019). "The decreasing of S100A9 might indicate the insufficient immunity, which explains the exacerbation induced by infection." (PMID 29942307, 2018). "Infection of HBV also resulted in an elevated S100A9 expression in L02 cells." (PMID 29615081, 2018). "Western blots indicated that protein production for IL-1β, S100A8, and S100A9 is significantly increased upon infection (lanes denoted by “I”), which confirms the RNA-seq data for the genes encoding these proteins and further validates the RNA-seq data as a whole." (PMID 25901897, 2015). "We could therefore demonstrate that locally expressed S100A9 is the first imaging marker predicting the development of a Th1 immune response, several weeks before the clinical outcome of infection." (PMID 25098555, 2014). "In the preceding studies, the high levels of S100A9 secretion during infection suggested that secreted extracellular S100A9 may have some role during IAV infection." (PMID 24391503, 2014). "After infection, medium supernatant was collected to assess S100A9 protein levels by ELISA." (PMID 24391503, 2014). "Pre-stimulation of NK cells by S100A9 tetramers induced a significant decrease in the percentage of CD3+ T cells replicating the virus, at day 7 and 10 post-infection, and this decrease was abrogated when NK cells were pre-stimulated with a combination of S100A9 tetramers and CD85j-Fc." (PMID 24156302, 2013).